OR6C75 (olfactory receptor family 6 subfamily C member 75)
Description:
Odorant receptor.
Tractability: Antibody: UniProt places it where antibodies can reach, with medium confidence; UniProt predicts a signal peptide or a membrane-spanning region; its Gene Ontology location is reachable by antibodies, with medium confidence.
Gene: Protein-coding gene on chromosome 12 (55,362,975 to 55,369,279, forward strand). Ensembl gene ENSG00000187857.
Subcellular location: Cell membrane
Pathways (Reactome):
Sensory Perception: Expression and translocation of olfactory receptors
Gene Ontology:
Molecular function: olfactory receptor activity; G protein-coupled receptor activity
Biological process: detection of chemical stimulus involved in sensory perception of smell; G protein-coupled receptor signaling pathway
Cellular component: plasma membrane; membrane
Genetic constraint (gnomAD): Loss-of-function variants: 0 observed, 0.76 expected, observed/expected ratio (o/e) 0, 90% interval 0 to 1.78. That is too few expected variants to judge how well the gene tolerates losing a copy. Missense variants: 379 observed, 386.7 expected, observed/expected ratio (o/e) 0.98, 90% interval 0.9 to 1.07. Synonymous variants: 149 observed, 136.73 expected, observed/expected ratio (o/e) 1.09, 90% interval 0.95 to 1.25.
Homologues: Orthologues: macaque OR6C75 (95% identical), rabbit OR6C75 (90% identical), mouse Or6c75 (87% identical), rat Or6c75 (87% identical), dog OR6C75C (83% identical), dog OR6C75 (83% identical). Paralogues in human: OR6C76 (73% identical), OR6C74 (72% identical), OR6C65 (72% identical), OR6C3 (71% identical), OR6C70 (71% identical), OR6C1 (70% identical), OR6C6 (69% identical), OR6C4 (67% identical), OR6C2 (66% identical), OR2AP1 (63% identical), OR6C68 (62% identical), OR6T1 (47% identical), and 6 more.